INS (insulin)
Diseases named in the same sentence as INS in open-access papers (continued):
Sharing a sentence is not in itself a finding about the gene and the disease.
type 2 diabetes (continued). "The aim of the study is to assess the effects of SMBG and SMUG in patients with type 2 diabetes who are not using insulin compared to usual care." (PMID 19397795, 2009). "Unlike insulin, metformin, an oralanti-diabetic drug, restores insulin sensitivity in type diabetes type II.Remarkably, metformin decreases the incidence of breast cancer." (PMID 20157517, 2009). "Although the obese subjects had higher plasma insulin and glucose concentrations than controls, none had overt type 2 diabetes." (PMID 20017959, 2009). "When lifestyle changes alone do not control blood glucose levels among people with type 2 diabetes, glucose lowering medications (OHAs or insulin) are introduced." (PMID 19917136, 2009). "In summary, the 30%-carbohydrate diet over 6 months led to a remarkable reduction in HbA1c levels, even among outpatients with severe type 2 diabetes, without any insulin therapy, hospital care or increase in sulfonylureas." (PMID 19419563, 2009). "SDT rat is a useful model of nonobese type 2 diabetes that spontaneously develops hyperglycemia and glucose intolerance resulting from decreased insulin secretion due to β-cell degeneration." (PMID 19696902, 2009). "The GK-rat is a non-obese model of type 2 diabetes that is characterised by glucose intolerance, insulin resistance, hyperinsulinaemia, altered insulin secretion and reduced beta cell mass." (PMID 19575795, 2009). "Oral and intravenous glucose stimulated insulin release (n = 849) and insulin sensitivity (n = 596) estimated from a hyperinsulinemic euglycemic clamp were measured in non-diabetic offspring of type 2 diabetic patients from five European populations." (PMID 19789630, 2009). "Participants were 59 people with Type 2 diabetes not taking insulin, recruited from general practice lists or opportunistically by general practice staff." (PMID 19228402, 2009). "Injecting bone marrow mononuclear cells directly into the pancreas significantly increased endogenous insulin secretion in type 2 diabetic patients, but not in persons with T1DM in studies conducted in Peru and Argentina." (PMID 19825196, 2009). "Patients (n=3856) with type 2 diabetes previously receiving human premixed insulin with or without oral antidiabetic drugs were eligible for inclusion." (PMID 19210701, 2009). "Glucose-stimulated insulin secretion is biphasic; impaired or absent first-phase insulin secretion is an early feature of type 2 diabetes, while second-phase insulin secretion deteriorates during progression of the disease." (PMID 19516902, 2009). "Mitochondrial ATP synthesis has been reported to be down in insulin resistant but non-diabetic offspring of parents with type 2 diabetes as well as in type 2 diabetic patients." (PMID 19668377, 2009). "Several study suggested the predominant effect of the genetic contribution to type 2 diabetes was mediated through defect in insulin secretion rather than action." (PMID 19862325, 2009). "While these studies provide some insight into US physicians’ attitudes about initiating insulin in patients with type 2 diabetes, they did not include PCPs, who care for the majority of patients with type 2 diabetes in the USA." (PMID 18393965, 2008). "Guidance has been published on the choice of initial insulin regimen for patients with type 2 diabetes [NPH (isophane) insulin or a long-acting insulin analogue] but not on how to choose a second regimen when glycaemic control becomes unsatisfactory." (PMID 19143853, 2008). "This means many people are treated as having type 2 diabetes at diagnosis as they are adults who are not immediately insulin dependent." (PMID 18652676, 2008). "The possible clinical implications of this study are that failing insulin secretion in type 2 diabetes should not be treated with pharmacological compounds that stimulate insulin release in a tonic fashion." (PMID 18959474, 2008).
type 2 diabetes (continued). "Many patients with type 2 diabetes treated with antidiabetic sulfonylureas (which inhibit KATP activity and thereby enhance insulin secretion) show long-term insulin secretory failure, which we further suggest might reflect a similar progression." (PMID 18959471, 2008). "In patients with type 2 diabetes who are poorly controlled with basal insulin (with or without OADs), simple intensification with BIAsp 30 over a 6-month period can significantly improve glycaemia without incurring hypoglycaemia or weight gain." (PMID 18479365, 2008). "Although high-dose STZ severely impairs insulin secretion mimickingtype 1 diabetes, low-dose STZ has been known to induce a mild impairment of insulin secretion which is similar to the feature ofthe later stage of type 2 diabetes." (PMID 19132099, 2008). "A more recent retrospective observational study using a national health-claims database reported the probability of a cardiovascular event to be 34% less for patients with type 2 diabetes on insulin than for those not on insulin." (PMID 18393965, 2008). "Based on their efficacy toimprove insulin sensitivity, the TZD PPARγligands rosiglitazone and pioglitazone are currently being utilized in clinicalpractice to treat insulin resistance in patients with type 2 diabetes." (PMID 18288288, 2008). "Further research into the role of negative affect in patients' perceptions of insulin therapy is warranted, as depression is common among people with type 2 diabetes, adversely affecting self-management and subsequent clinical outcomes." (PMID 18096074, 2007). "The combination of basal and prandial therapy is an important option for patients with type 2 diabetes when glycemic control is not achieved with OADs alone or basal insulin plus OAD therapy." (PMID 17448241, 2007). "Timely initiation of insulin therapy in type 2 diabetes is important to achieve metabolic control but can be hindered by negative perceptions of patients regarding insulin treatment." (PMID 18096074, 2007). "Adults living with type 2 diabetes, with an HbA1c > 8% and not taking insulin were initially eligible." (PMID 17598895, 2007). "Daily lignan supplementation resulted in modest, yet statistically significant improvements in glycemic control in type 2 diabetic patients without apparently affecting fasting glucose, lipid profiles and insulin sensitivity." (PMID 17987126, 2007). "This section provides practical recommendations for initiating basal and prandial insulin in patients with type 2 diabetes who are not achieving glycemic targets on OADs alone." (PMID 17448241, 2007). "In the absence of insulin treatment, these are the principle mechanisms by which glucose control can be maintained on an hour by hour basis for people with type 2 diabetes." (PMID 16846517, 2006). "Eligibility criteria are adults able to undertake the programme with type 2 diabetes, not taking insulin, with HbA1c over 8% (first 12 months) and following an agreed protocol change over 7% (months 13 to 18)." (PMID 16846517, 2006). "The lack of good evidence has prompted some opinion leaders to suggest that SMBG for people with type 2 diabetes not receiving insulin is a "waste of money"." (PMID 17164006, 2006). "A 1-year study in patients with type 2 diabetes treated with telmisartan or eprosartan found that only telmisartan improved plasma lipid profiles, but did not significantly affect glycemia or insulin sensitivity." (PMID 15892894, 2005). "It should be noted that participants in the cited study consisted of insulin‐sensitive and insulin‐resistant individuals, but not people living with type 2 diabetes, who exercised until exhaustion, whereas participants in the present study had confirmed T2DM and performed submaximal exercise." (PMID 40551391, 2026).
type 2 diabetes (continued). "Some researchers established a Type 2 Diabetes Mellitus model for colorectal cancer, and revealed that the activation of ERK1/2 and JNK signaling by insulin and IGF-1, at least in part, is responsible for the development of colon cancer with T2DM." (PMID 40406485, 2025). "A study on type 2 diabetic patients using Twin Precision Nutrition observed significant improvements in metabolic health markers (e.g., Hba1C, weight, HOMA-IR), with most patients ceasing the use of medications (including insulin, metformin, DPP-4 inhibitors, and liraglutide)." (PMID 41305566, 2025). "Adding fats can delay and prolong the glycemic response, while protein intake in patients with type 2 diabetes may increase insulin response without raising blood glucose levels." (PMID 39939862, 2025). "In addition to the lack of transcriptional response related to glycolysis and glycogenolysis between the trained and untrained legs in type 2 diabetes, DEGs related to the KEGG insulin signalling and insulin resistance pathways were distributed across all three fibre types in that group." (PMID 40413649, 2025). "Given mTOR’s involvement in regulating metabolism, mTOR inhibitors like rapamycin have also been explored for metabolic disorders such as type 2 diabetes and non-alcoholic fatty liver disease (NAFLD), where they may improve insulin sensitivity, lipid metabolism, and reduce inflammation." (PMID 40299431, 2025). "Type 3 diabetes has been interpreted by some researchers to describe the concept that impaired insulin and insulin-like growth factor (IGF) signaling in the brain, similar to what happens in type 2 diabetes, may play a significant role in the development of AD." (PMID 39857716, 2025). "Similarly, islets isolated from healthy donors but not from individuals with type 2 diabetes secrete insulin in response to IL-1β." (PMID 39496966, 2025). "Furthermore, uric acid interferes with the insulin signaling pathway by attracting ectonucleotide pyrophosphatase/phosphodiesterase 1 (ENPP1) to the insulin receptor, thereby worsening the progression of type 2 diabetes." (PMID 41301787, 2025). "This oxidative stress damages pancreatic β cells’ ability to produce insulin, weakens target tissues’ responsiveness to insulin signaling, and compromises vascular endothelial function, regardless of whether patients have type 1 or type 2 diabetes." (PMID 40565712, 2025). "We conducted a prospective, single-center, open-label, nonrandomized, controlled clinical study in patients with type 2 diabetes stably treated with insulin, who were assigned to dapagliflozin (5 mg/day with dose-reduced insulin; n=8/9 completed) or insulin dose-up (n=5/8 completed)." (PMID 41282284, 2025). "Simultaneously, first-phase insulin response to a stepped intravenous glucose infusion improved and was normalized in individuals with type 2 diabetes, whereas first-phase insulin response did not change 8 weeks after surgery in individuals with normal glucose tolerance." (PMID 41009753, 2025). "Finally, a retrospective study of individuals receiving care from an American Medical Group Association (AMGA) member organisation found an A1c decrease of −1.13% among people with type 2 diabetes not on insulin therapy with a baseline A1c ≥ 7.5%." (PMID 40851538, 2025). "Unlike Type 1 diabetes, individuals with Type 2 diabetes do not initially require insulin therapy." (PMID 39854291, 2025). "Therefore, it will be important to investigate further how AldoB overexpression in islets of patients with type 2 diabetes affects beta cell AMPKα/mTOR activities, mitochondrial function, the dynamics of G3BP1+/INS mRNA condensates, and thus insulin production and secretion." (PMID 40355555, 2025). "This leads to insulin resistance, pancreatic β-cell dysfunction, and reduced insulin synthesis via inhibition of pancreatic duodenal homeobox-1 (PDX-1) and glucose transporter type 2 (GLUT2), ultimately contributing to hyperglycemia and type 2 diabetes mellitus (T2DM)." (PMID 40810768, 2025).
type 2 diabetes (continued). "Despite work suggesting pancreatic β‐cells are under circadian system regulation and people with obesity/type 2 diabetes have blunted diurnal patterns, no work has been done to examine glucose‐stimulated insulin secretion and pancreatic function in people with different chronotypes." (PMID 40018087, 2025). "Given its multifaceted roles in improving insulin sensitivity, glycemic control, lipid metabolism, body weight regulation, and inflammatory responses, GPR35 has emerged as a promising therapeutic target for metabolic disorders such as type 2 diabetes mellitus (T2DM), obesity, and NAFLD." (PMID 41459506, 2025). "This is interesting because HPLC diets are often used in the treatment of type 2 diabetes for their reported ability to lower glucose and increase insulin sensitivity, suggesting a potential role for the elevated ARA in the blood of individuals fed HPLC diets in the prevention of type 2 diabetes." (PMID 40051529, 2025). "Immunization with SAS-adjuvanted OmpW elicited strong serum antibody responses, along with IFN-γ-secreting CD4+, CD8+, natural killer, and natural killer T cell responses against OmpW in non-insulin-resistant C57BL/6J and insulin-resistant C57BL/6J mouse models of Type 2 diabetes." (PMID 40630947, 2025). "However, other cases had a phenotype close to type 2 diabetes or did not require lifelong insulin therapy." (PMID 39925806, 2025). "This hypothesis is supported by evidence from an outcome trial comparing different treatment regimens for type 2 diabetes, including glucagon-like peptide-1 receptor agonists (GLP-1RA), sodium-glucose co-transporter 2 inhibitors (SGLT-2i), and insulin monotherapy." (PMID 40251633, 2025). "Collectively, our results support the notion that impaired insulin action, rather than obesity per se, may be the primary factor contributing to elevated plasma BCAAs, as observed in the individuals with type 2 diabetes in our study." (PMID 40404819, 2025). "In this randomized clinical trial of 149 adults with type 2 diabetes, the glycemic control of the artificial intelligence–based insulin clinical decision support system intervention was not inferior to that of standard therapy by senior physicians, without increasing risk of adverse events." (PMID 40332936, 2025). "In addition, females in the DD group had a significantly higher presence of type 2 diabetes compared to those without DD symptoms and had a significantly higher intake of anti-diabetic and pain medications, including insulin and analgesics." (PMID 40699752, 2025). "However, it is not fully determined how insulin resistance and type 2 diabetes are related to AD‐related brain glucose metabolism abnormalities." (PMID 40033766, 2025). "Type 2 diabetes is due to a relative lack of insulin, wherein the body is capable of synthesising bioactive hormone, but unable to respond to it, which one can call a relative lack of insulin." (PMID 41018406, 2025). "Both clinical trials and meta-analyses indicated that high (1 g/day) and low (5 mg twice daily) dosages of resveratrol were able to improve blood glucose, insulin sensitivity, and oxidative stress in type 2 diabetics but not in non-diabetics, pointing towards the need for more specific research." (PMID 41515205, 2025). "In addition to blood pressure, type II diabetes is also known to be associated with deep sleep, and the duration of non-REM sleep stage 3 has been reported to affect insulin sensitivity, and is important for blood glucose control." (PMID 41425166, 2025). "Importantly, we demonstrated that insulin’s ability to suppress plasma BCAAs is impaired in individuals with type 2 diabetes compared with glucose-tolerant individuals with and without obesity in three of our studies." (PMID 40404819, 2025).
type 2 diabetes (continued). "A recent meta-analysis of IER [5:2 and ADF] vs. CER studies amongst individuals with type-2 diabetes or the metabolic syndrome [4 studies 355 participants] concluded IER was safe in these populations and had comparable effects with CER on glycaemic control, fasting insulin and lipid profiles." (PMID 41146360, 2025). "Notably, in Goto-Kakizaki (GK) rats—a model of type 2 diabetes—pharmacological enhancement of O-GlcNAcylation in pancreatic islets leads to impaired GSIS, highlighting the critical role of O-GlcNAcylation in the regulation of insulin secretion." (PMID 41373704, 2025). "Other non-randomized studies showed a slight reduction in fasting glucose or Hb1Ac, however most of the randomized controlled studies in patients with obesity but without type 2 diabetes agree that TRE do not have a significant impact on glycemic control or insulin sensitivity." (PMID 39899119, 2025). "Altogether, these findings suggest that M. charantia may improve glycaemia by enhancing insulin sensitivity rather than stimulating β-cell insulin secretion in individuals with prediabetes and type 2 diabetes." (PMID 41280283, 2025). "Moreover, we demonstrate that the insulin-mediated suppression of plasma BCAAs was not potentiated by acute exercise in either individuals with type 2 diabetes or glucose-tolerant individuals with obesity." (PMID 40404819, 2025). "A largely uniform approach to the use of metformin and insulin in the management of Type 2 diabetes in pregnancy has resulted in a lack of studies evaluating optimal dosing or regimens that may optimise glycaemia." (PMID 39527377, 2025). "Treatment of hyperglycaemia in type 3c diabetes is not clearly differentiated from that for type 1 and type 2 diabetes, with current recommendations limited to considering early insulin initiation and avoidance of incretin‐based therapies due to their potential association with pancreatitis." (PMID 39762966, 2025). "In contrast to autoimmune type 1 diabetes, in which the body’s own vital insulin can no longer be produced and must be replaced, in type 2 diabetes the transport of blood glucose into the cells is restricted due to a reduced insulin effect (insulin resistance)." (PMID 39081466, 2024). "Type 2 diabetes arises due to the inefficient use of insulin by the body, and over time, the pancreas may not produce enough insulin." (PMID 39683757, 2024). "In metabolic disorders (including obesity and type 2 diabetes), adipose tissue frequently exhibits elevated basal lipolysis, which leads to chronically high FFA levels or ectopic lipid deposition, and further impairing insulin signaling both in the liver and skeletal muscle." (PMID 39749015, 2024). "Thus, although there was a temporal increase in insulin extraction in those with type 2 diabetes, this should not be interpreted that the hepatic handling of insulin is intact or functional." (PMID 39138690, 2024). "While our data suggest that the impaired suppression of ICR is a primary hepatic defect, this may not be the case for people with more advanced type 2 diabetes and reduced insulin secretory capacity." (PMID 39138690, 2024). "Importantly, repression of the PGC-1α-dependent mitochondrial program has long been documented in skeletal muscles of individuals with type 2 diabetes, and PGC-1α dysregulation and hence mitochondrial insufficiency are widely acknowledged contributors to muscle insulin resistance." (PMID 38216792, 2024). "In type 2 diabetes, counterregulatory responses have both been reported to be unaffected or reduced, with counterregulatory failure being described in those with reduced beta-cell function in longstanding disease and the prevalence of IAH averaging 10% in those using insulin." (PMID 38376580, 2024).